VCAM1 (vascular cell adhesion molecule 1)
Diseases named in the same sentence as VCAM1 in open-access papers (continued):
Sharing a sentence is not in itself a finding about the gene and the disease.
tumor (continued). "On the contrary, non-ablative UTMC, in addition to increasing local drug concentration, enhances anti-tumor responses by inducing vascular inflammation (ICAM-1, VCAM-1), facilitating CTL infiltration, decreasing cancer cell proliferation, and promoting immunogenic cell death." (PMID 38543305, 2024). "Both anti-CD49d antibody and anti-VCAM1 antibody did not influence MC38 tumor cell apoptosis in vitro." (PMID 38332012, 2024). "Notably, we found that USP7 inhibition increased gene expression levels of ICAM‐1 (log2 fold changes = .85, padj = .017), VCAM‐1 (log2 fold changes = .72, padj = 1.9 × 10−4), and ITGB‐2 (log2 fold changes = 1.26, padj = 1.84 × 10−4) in the tumour." (PMID 38602256, 2024). "Our study suggests that VCAM1-CD49d signaling is not essential for iNKT cell activation in tumors, and is dispensable for tumor cell clearance." (PMID 38332012, 2024). "We found that CD1d overexpression in MC38 tumor cells showed no influence on anti-tumor efficacy of iNKT cells, and knockdown of Vcam1 efficiently elevated anti-tumor efficacy of iNKT cells in CD1d expressing MC38 tumor models." (PMID 38332012, 2024). "Vascular endothelial growth factor (VEGF) and fibroblast growth factor 2 (FGF2) secreted by tumor cells induce tumor endothelial cells anergy by inhibiting the upregulation of ICAM-1, VCAM-1, and selectins on tumor endothelial cells under inflammatory stimulation." (PMID 39325128, 2024). "Tumor ICAM-1 and VCAM-1 are a modality for tumor dissemination." (PMID 38786066, 2024). "Indeed, PLX3397 and anti-VCAM1 in combination better enhanced anti-tumor efficacy of transferred expanded iNKT cells than PLX3397 alone and anti-VCAM1 alone." (PMID 38332012, 2024). "Moreover, in vitro co-culture experiments have revealed that vascular cell adhesion molecule-1 (VCAM1) contributes to PNI and accelerates GC progression by promoting interactions between nerve cells and tumor cells." (PMID 38081962, 2024). "Since then, various tumor-targeting nanomaterials have been developed to connect tissue factor extracellular regions and deliver various cytokines to the tumor site, such as L19, NGR, VEGF, chTNT-3, VCAM-1 and RGD." (PMID 37452423, 2023). "For instance, aberrant expression of VEGF can prevent the trafficking of tumor-reactive T cells to the tumor site by inhibiting the expression of adhesion molecules, such as intercellular adhesion molecule 1 (ICAM-1) and vascular cell adhesion molecule 1 (VCAM-1) within endothelial cells." (PMID 36357599, 2023). "To evaluate the contribution of integrin-mediated cell adhesion to T-ALL progression after tumor establishment, we administered an anti-ICAM-1 blocking antibody alone or in combination with an anti-VCAM-1 blocking antibody after LN3 leukemic burden reached 1–8% in the spleen." (PMID 37805579, 2023). "Vcam1 is not directly involved in cell proliferation but support iCCA tumor mass expansion under pMF suppression and restrain tumor cell dissemination." (PMID 36828890, 2023). "Some of these genes were upregulated in our analyses of skin KS (BTAF, VMP1, DCHS1, VCAM1, PLXND1)." (PMID 37740179, 2023). "Moreover, HA stimulates EC tube formation via CD44 and CD168/TGFβ Receptor I signaling, which promote plasminogen activator-inhibitor-1 (PAI-1) expression and subsequently ICAM-1, VCAM-1, and MMP-2 expression, thereby promoting tumor angiogenesis." (PMID 37350937, 2023). "In patients with tumor grade G1, the median VEGF-R2, VEGF-R3, and VCAM-1 values were not significantly different from those in the group with tumor grade G2 (p > 0.05)." (PMID 36979820, 2023). "C3 significantly reduced the expression (mRNA level) of inflammatory molecules TNF-α, pro-IL-β, ICAM-1, and VCAM-1 in the tumor tissue, unlike cisplatin, which significantly reduced the expression of pro-IL-β and ICAM-1." (PMID 37569878, 2023).
tumor (continued). "The expression of the adhesion molecules vascular cell adhesion protein 1 (VCAM1) and intercellular adhesion molecule 1 (ICAM1) is inhibited by dysfunction of the vascular system in tumor tissues, which inhibits the effective infiltration of T cells and magnifies the inhibitory effect." (PMID 38115906, 2023). "Treatment with l-Nω-methylarginine (l-NMA, NOS inhibitor) and N-acetyl cysteine (NAC, an antioxidant that also inhibits S-nitrosylation) inhibited endothelial VCAM-1 cell surface expression, VCAM-1-S-nitrosylation, tumor cell transmigration through the endothelium and metastasis formation." (PMID 37773178, 2023). "Furthermore, compared to nonresponders, responders to anti‐PD1 monotherapy had increased VCAM1+ STING+ vessel counts found in close vicinity to CD8+ T‐cells and the fraction of effector PD1+/GrzB+ CD8+ T‐cells, particularly at the tumor–stroma interface." (PMID 38009521, 2023). "In a murine model of melanoma overexpressing IL-12 (B16-IL-12), NKp46+ ILC3 were shown to infiltrate the tumor and mediate the upregulation of ICAM-1 and VCAM-1 adhesion molecules on tumor vessels leading to the generation of a pro-inflammatory microvascular environment." (PMID 37234993, 2023). "Among them, the top up-regulated genes in tumor cells were those related to cancer progression (eg, AREG, CCL3, PLEKHA5, VCAM1 and MCM7), which might be the targets of innovative treatments." (PMID 36417130, 2023). "Other studies have found that tumor derived endothelial cells highly express mucosal epithelial cell adhesion molecule-1 (MADCAM-1), vascular cell adhesion molecule-1 (VCAM-1), and the ligands of these adhesion molecules are specifically expressed on Treg cells." (PMID 37064113, 2023). "SCAMs represent a unique tumor-specific TREM2+ population defined by VCAM1 surface expression that is not found in normal homeostatic skin or during wound healing." (PMID 37164949, 2023). "VCAM1 binds VLA-4 and both of them are expressed in tumor cells and brain endothelial cells." (PMID 37108248, 2023). "In both groups, DTCs showed no Vcam1 positivity, aSMA+ fibroblasts were commonly found around the Vcam1+ tumor cells." (PMID 36828890, 2023). "Following intravenous injection of VCAM-MPIO, however, MDA231Br-GFP tumor-bearing rats showed significantly increased volumes of hypointensities in the tumor-bearing striatum, consistent with binding of VCAM-MPIO to upregulated endothelial VCAM-1." (PMID 35312755, 2022). "Moreover, the expression of integrin α4β1, which supports communication between tumor cells, stromal cells, and vascular cells by binding with intercellular adhesion molecule-1 (ICAM-1) and vascular cell adhesion molecule-1 (VCAM-1)." (PMID 35203510, 2022). "This is consistent with the possibility that cells other than T cells might upregulate the expression of HRL, particularly VCAM-1 and CXCL9, on early-stage tumor endothelial cells." (PMID 36531040, 2022). "The strong interaction between VCAM-1 and VLA-4 was hypothesized to enable VLA-4+ monocytes and MACs to recruit tumor cells into the lung tissue." (PMID 36497180, 2022). "STAT6 can influence tumor angiogenesis through factors such as VCAM-1 and MMP, and NRP1 is not the only target molecule of STAT6." (PMID 35600336, 2022). "Vascular cell adhesion molecule 1 (VCAM-1) belongs to the family of immunoglobulin (Ig) proteins and is overexpressed on the surface of endothelial cells in many cancers, and VCAM-1 can take responsibility for tumor proliferation and metastasis." (PMID 35203695, 2022). "Secondly, a bunch of critical adhesion molecules including vascular cell adhesion molecule 1 (VCAM-1) and intercellular adhesion molecule 1 (ICAM-1) expressed on ECs are significantly down-regulated in newly formed tumor blood vessels, which hampers the adhesion and transmigration of T cells." (PMID 36439137, 2022).
tumor (continued). "Tumor vasculature is an important physical barrier for T cells due to the imbalance of adhesion molecules, such as intercellular adhesion molecule 1 (ICAM1), vascular cell adhesion protein 1 (VCAM1), and mucosal addressing cell adhesion molecule 1 (MAdCAM1)." (PMID 35296094, 2022). "Moreover, the low expression of adhesion molecules including ICAM-1 and 2, VCAM-1 and CD34 in tumor endothelial cells (EC) inhibit the effector T-cell from adhering to the EC and being transported to the tumor." (PMID 35401561, 2022). "VCAM-1, ICAM-1, and CXCL9 are key HRL for infiltration of CD8+ T cells in several tumor models." (PMID 36531040, 2022). "In an in vitro model of single-cell suspensions prepared from lung metastatic nodules, VCAM-1 was able to bind to MAMs, the most abundant source of potential α4-integrin, and vascular endothelial cells but not to neutrophils or tumor cells." (PMID 36294305, 2022). "Simvastatin could decrease CCL3 expression from cancer cells and ICAM-1, VCAM1, IL-6, and CCL2 expression from CaMSCs, disrupting the crosstalk of the cancer cells and tumor microenvironments (TME) and inhibiting tumor progression." (PMID 36430409, 2022). "VCAM-1 is not expressed or rarely expressed in normal cells, but it is abnormally highly expressed in many tumor tissues." (PMID 36482940, 2022). "Our findings on the specific post-activation subset of platelets that actively promoted endothelial integrity via VCAM-1 presentation provides a perspective on platelet-mediated anti-tumor effect that to our knowledge has not been fully explored previously." (PMID 35408794, 2022). "Such conditions, combined with the induction of expression of adhesion molecules such as vascular cell adhesion molecule 1 (VCAM-1) and intercellular adhesion molecule 1 (ICAM-1) (also mediated by TGF-β), are conducive to immune cell infiltration into the tumor microenvironment." (PMID 36499660, 2022). "Adhesional factors on the BBB endothelium such as ICAM-1, VCAM-1, or ACKR1 may be upregulated by IL-1β or IFN-γ, which can be delivered via convection-enhanced delivery (CED) directly to the tumor site." (PMID 34771532, 2021). "Notably, vascular cell adhesion molecule 1 (VCAM1) was up-regulated in CAFs compared with NFs from both the liver and skin, indicating that VCAM1 was consistently increased in CAFs and might be a candidate target for anti-tumor therapy in metastatic colon cancer." (PMID 34769102, 2021). "We showed that the expression of proteins specific to ECs (ACE+, VWF+), their differentiation (CD31+, CD 133+, CD105+, CD34-), their adhesion properties (ICAM-1+, VCAM-1+, CD62-L+), and their barrier formation (ZO-1+) were all downregulated in tumor-derived ECs." (PMID 34445568, 2021). "In the tumor environment, ECs are capable of expressing and using components of the RAAS signaling pathway to promote tumor growth, enhance angiogenesis and promote metastasis by providing components such as VEGF, a pro-angiogenic agent, and adhesion molecules such as VCAM1." (PMID 34281199, 2021). "We found VCAM1 expression as a significant prognostic factor independent of tumor grade with HR > 1, indicating that it is significantly associated with shorter survival with 95% CI (p = 0.03)." (PMID 33853689, 2021). "Agonist mAb stimulated tumor ECs, could increase expression of the ICAM-1, VCAM-1, and E-selectin on the surface of ECs, which are essential for CTLs to cross vessels and transport into TME." (PMID 34930293, 2021). "However, miR-144 or miR-451a promoted the expression of M1-like macrophage markers Marco, Vcam1, MHC II and CD86 in tumor tissues." (PMID 33658044, 2021). "In this process, LSECs upregulate the expression of cell adhesion molecules, such as vascular cell adhesion molecule 1 (VCAM-1), intercellular cell adhesion molecule 1 (ICAM-1), and E-selectin to support the arrest, retention, and transmigration of the tumor cells." (PMID 34067719, 2021).
tumor (continued). "Furthermore, we discovered that there is significantly positive correlation between extent of VCAM1 staining (Low, Medium or High) and percentage of TNF-alpha expressing GAMs cells per mm2 tumor area (Spearman, R = 0.8, p = 2.738e-009)." (PMID 33853689, 2021). "Immune-cells infiltration within the tumor requires the expression of adhesion molecules at the endothelial cell surface such as intracellular adhesion molecule 1 (ICAM1), vascular cell adhesion protein 1 (VCAM1) and CD34." (PMID 34064508, 2021). "Targeted MRI based on microparticles of iron oxide (MPIOs) has been used for visualization of the endothelial vascular cell adhesion molecule-1 (VCAM-1) in the mouse brain, where it was shown that VCAM-1 expression, detected by MRI, increased significantly with tumor progression." (PMID 34988446, 2021). "Second, given that VCAM-1 seemed to have effects on tumor growth and gemcitabine resistance in allograft models, anti-VCAM-1 antibody monotherapy may also have tumor inhibitory effects." (PMID 33273652, 2020). "In the current study, we explored the potential mechanism of Porf-2 in tumor cell migration by screening several key proteins, such as adhesion molecules (ICAM1, VCAM1, E-cadherin), chemokines (CCL4, CXCL4) and their receptors (CXCR4/6/7), integrins (integrin α1/β1/β3), and MMPs (MMP-2/3/7/9)." (PMID 32676454, 2020). "Further experiments are needed to determine whether VCAM-1 inhibition prolongs survival of mice with PDAC, and delays tumor development in PKF mice." (PMID 33273652, 2020). "Monte Carlo simulation of radiation dose deposition showed that 212Pb-labeled anti–VCAM-1 antibodies would provide a therapeutic dose to tumor cells adjacent to blood vessels, without the need for antibodies to cross the BBB." (PMID 31538194, 2020). "Consequently, EGF can induce an upregulation of vascular cell adhesion molecule-1 (VCAM-1) that favors the interaction between TAMs and tumor cells, which in turn promoted tumor cell invasion." (PMID 32322199, 2020). "Consistent with the in vitro results, mice injected with ESM-1-overexpressing 4T1 cells exhibited significant increases in tumor volume, lung metastasis, metastasis-related molecules (VEGF, MMP-9, ICAM-1, and VCAM-1), and transcription factors (HIF-1α, phospho-NF-κB, and phospho-STAT-3)." (PMID 32466580, 2020). "Mechanistically, the HPC-maintaining capacity of the bone marrow was significantly impaired in tumor-bearing mice, with lower expression of HPC maintaining genes (i.e., CXCL12, SCF, ANGPT1, and VCAM1), and reduced levels of mesenchymal stem cells and CXCL12-producing cells." (PMID 33603745, 2020). "Anti-VCAM-1 and anti-IL4Rα DNA aptamers specific to VCAM-1 and IL4Rα receptors that are overexpressed in 4T1 tumor-bearing mice could be used as potential biomarker for both diagnostic and therapeutic applications in cancer biology." (PMID 32751068, 2020). "LSEC expression of distinct adhesion molecules and growth factors could drive BM-EPCs recruitment, especially since BM-EPC homing to tumour tissue is thought to be via cellular adhesion molecules ICAM-1, VCAM-1, and VEGF." (PMID 32982772, 2020). "Tumor volume, lung metastasis, and tumorigenic molecules (VEGF-A, HIF-1α, MMP-9, ICAM-1, VCAM-1, and phospho-NF-κB and phospho-STAT-3) were significantly induced in mice injected with ESM-1-overexpressing 4T1 cells and greatly enhanced in those injected with ESM-1-overexpressing RT-R-4T1 cells." (PMID 32466580, 2020). "While tumor cell growth was not affected by VCAM-1 in 2D culture, we observed increased tumor growth in allograft models." (PMID 33273652, 2020). "However, it has been shown that anti-angiogenic drugs normalize the tumor vasculature and induce the upregulation of the leukocyte adhesion molecules ICAM-1 and VCAM-1 on tumor endothelial cells, leading to increased T cell infiltration." (PMID 30800125, 2019).
tumor (continued). "VCAM-1 expression could be induced by pro-inflammatory cytokines, such as Tumor Necrosis Factor-α (TNF-α), IL-1 or IL-6, major mediators of tumor progression." (PMID 31340603, 2019). "Moreover, animal experiments where mCherry-targeted tumor cells were quantified by flow cytometry to exclude endothelial cells which actively express VCAM-1, confirmed that CAFs can promote VCAM-1 expression in cancer cells and macrophages recruitment." (PMID 30894509, 2019). "As postulated in this study, the proportion of apoptosis in the tumor cells, which were gated as TUNEL+ mCherry+, was decreased after co-injection of BM-MSC, but these effects of BM-MSC were eliminated after the depletion of macrophages or VCAM-1 knockdown." (PMID 30894509, 2019). "Furthermore, these molecules also promote the release of IFN-γ (type II IFN) and upregulate VCAM-1 and MHC-I expression on tumor cells and antigen-presenting cells (APCs), which in turn promote the presentation of tumor antigens." (PMID 31455032, 2019). "Surprisingly, VCAM1 depletion in tumor cells had no influence on the ability of cancer cells to cross the endothelium, rather, this vasculogenic mimicry phenotype enhanced the ability of cancer cells to colonize and remain viable within the secondary niche." (PMID 31497019, 2019). "First, high activity in blood was also observed, which renders T/B ratios (1.25 ± 0.08) not ideal in VCAM-1 positive tumor models at 1 h." (PMID 29853809, 2018). "There are some studies supporting the expression-promoting role of VEGF in adhesion molecules including VCAM-1, but most of them are not based on tumor models." (PMID 29774034, 2018). "This allows components of the blood to readily extravasate into the tumour interstitium and facilitates the transmigration of lymphocytes, which is mediated by intracellular adhesion molecule 1 (ICAM-1), vascular cell adhesion molecule 1(VCAM-1), and E-selectin." (PMID 30261606, 2018). "In addition, the downregulation of adhesion molecules, such as vascular cell adhesion molecule 1 (VCAM1) and intercellular adhesion molecule 1 (ICAM1), leads to an enhancement of a tumor vasculature barrier that inhibits T cell arrest and transmigration." (PMID 30115069, 2018). "Interestingly, the PT-induced upregulation of ICAM-1, VCAM-1 and CXCL12 were dispensable for the PT-evoked tumor cell adhesion." (PMID 29100413, 2017). "Tumor endothelium, by its unique position, regulates the trafficking of leukocytes into tumors by controlling the expression of adhesion molecules such as intercellular adhesion molecule-1 (ICAM-1) or vascular cell adhesion molecule-1 (VCAM-1)." (PMID 29104248, 2017). "Further, only L-Selectin and not VCAM-1 was significantly overexpressed in the primary tumours of PTC patients when compared to that in patients with benign thyroid diseases." (PMID 26881177, 2016). "As for the transcripts, we detected VCAM-1 mRNA in the primary and first generation implanted tumor but not at the metastatic stage." (PMID 26847082, 2016). "Our results have shown that the expression of endothelial adhesion molecules as VCAM-1 and ICAM- 1 was notably increased in B16F10-ARF−/− tumor xenografts which may also contribute to macrophages recruitment." (PMID 27572316, 2016). "For example, IL-1β, a special form of IL-1, can stimulate expression of VEGF and TNFα to promote tumor angiogenesis and adhesion molecules, including intercellular-adhesion molecule 1 (ICAM-1), vascular cell adhesion molecule 1 (VCAM-1) and E-selectin, to enhance invasion." (PMID 24338768, 2014). "Transcripts of other genes such as matrix metallopeptidase-9, serpin-1 and vascular cell adhesion molecule-1 were not affected in tumor tissue that survived ablation." (PMID 24270800, 2014). "Continuous section slides were stained for ICAM-1, VCAM-1 and CIK cells respectively to figure out the spacial relationship between CIK cells infiltration and the endothelial cell adhesion molecules within the tumor." (PMID 23799045, 2013).